ZCCHC12 (zinc finger CCHC-type containing 12)
Description:
Transcriptional coactivator in the bone morphogenetic protein (BMP)-signaling pathway. It positively modulates BMP signaling by interacting with SMAD1 and associating with CBP in the transcription complex. It contributes to the BMP-induced enhancement of cholinergic-neuron-specific gene expression (By similarity).
Synonyms: SIZN1; FLJ16123; SIZN; PNMA7A
Tractability: PROTAC: ubiquitination databases record sites on it.
Gene: Protein-coding gene on chromosome X (118,823,824 to 118,826,968, forward strand). Ensembl gene ENSG00000174460.
Subcellular location (Human Protein Atlas): Nuclear bodies
Gene Ontology:
Molecular function: protein binding; nucleic acid binding; zinc ion binding
Cellular component: nucleus
Homologues: Orthologues: chimpanzee ZCCHC12 (99% identical), macaque ZCCHC12 (97% identical), dog ZCCHC12 (84% identical), guinea pig Zcchc12 (80% identical), mouse Zcchc12 (74% identical), rat Zcchc12 (73% identical), dog ZCCHC18 (70% identical), rat Zcchc18 (69% identical), mouse Zcchc18 (68% identical). Paralogues in human: ZCCHC18 (84% identical), PNMA3 (23% identical), PNMA5 (23% identical), PNMA6A (23% identical), PNMA1 (22% identical), PNMA6E (21% identical), PNMA2 (21% identical), PNMA6F (20% identical), MOAP1 (18% identical), CCDC8 (12% identical), PNMA8A (9% identical), PNMA8B (8% identical), and 1 more.
Diseases named in the same sentence as ZCCHC12 in open-access papers:
ZCCHC12 is named in the same sentence as 11 diseases in open-access papers, as found by Europe PMC text mining. Sharing a sentence is not in itself a finding about the gene and the disease. The quoted sentences say what the papers report.
osteosarcoma (4 papers, 2022 to 2025). A usually aggressive malignant bone-forming mesenchymal neoplasm, predominantly affecting adolescents and young adults. "As part of our present study, we investigated the underlying biochemical mechanisms of ZCCHC12 and its impact on osteosarcoma." (PMID 36126191, 2022). "As a result of activating the PI3K/AKT pathway, ZCCHC12 promotes osteosarcoma tumorigenesis, while inhibition of PI3K/AKT pathway limits its effectiveness in osteosarcoma." (PMID 36126191, 2022). "Analysis of whole transcriptome in osteosarcoma showed that osteosarcoma exhibits an upregulation of ZCCHC12 in comparison to normal bone tissues." (PMID 36126191, 2022). "Furthermore, studies have shown that ZCCHC12 promotes the progression of osteosarcoma via PI3K/AKT pathway." (PMID 37848968, 2023). "Cell cycle arrest occurs when ZCCHC12 is knocked down in osteosarcoma cells." (PMID 36126191, 2022). "Thus, investigation of the influence of ZCCHC12 on osteosarcoma tumorigenesis is crucial." (PMID 36126191, 2022). "Meanwhile, we found that osteosarcoma cells may be induced to proliferate and migrate by ZCCHC12." (PMID 36126191, 2022). "Our study indicates that ZCCHC12 may be a novel therapy target of osteosarcoma." (PMID 36126191, 2022). "ZCCHC12 can promote the progression of osteosarcoma through the PI3K/AKT pathway, and ZCCHC12+ tumor cells in papillary thyroid cancer interact with CD36+ pro-inflammatory macrophages to promote tumor progression and recurrence." (PMID 41438761, 2025). "However, the biological role of ZCCHC12 in osteosarcoma (OS) remains unknown." (PMID 36126191, 2022). "Despite this, no functional role has been revealed for ZCCHC12 in osteosarcoma occurrence or development." (PMID 36126191, 2022).
thyroid cancer (4 papers, 2021 to 2024). "ZCCHC12 has been reported to serve as a transcriptional coactivator in the BMP pathway and was associated with some diseases such as thyroid carcinoma." (PMID 36126191, 2022). "Moreover, bioinformatics analysis also revealed high ZCCHC12 expression in thyroid carcinoma tissue samples and normal tissue samples." (PMID 34950770, 2022).
papillary thyroid cancer (3 papers, 2022 to 2025). "Studies have shown that ZCCHC12 down-regulation significantly inhibited the colony formation, migration, and invasion, in an in vitro assay in papillary thyroid cancer cells." (PMID 37848968, 2023). "Researchers have reported that zinc finger CCHC domain containing 12 gene (ZCCHC12) plays a role in the progression and tumorigenesis of papillary thyroid cancer." (PMID 36126191, 2022).
esophageal cancer (1 paper, 2022). A primary or metastatic malignant neoplasm involving the esophagus. "Mahmoudian and Forghanifard discovered that correlation between different cell signaling pathway-related genes, including ZCCHC12, may lead to the tumorigenesis of esophageal cancer." (PMID 34950770, 2022).
gastric cancer (1 paper, 2022). A primary or metastatic malignant neoplasm involving the stomach.
glioma (1 paper, 2025). A benign or malignant brain and spinal cord tumor that arises from glial cells (astrocytes, oligodendrocytes, ependymal cells). "The differential expression analysis results showed that the mRNA expression levels of FXYD1, ZCCHC12, and PDE2A were highly expressed in normal brain tissues, while the other six genes were significantly upregulated in glioma samples." (PMID 41438761, 2025).
thyroid (1 paper, 2022). "High ZCCHC12 expression in thyroid malignancy has been revealed by bioinformatics analysis and previous studies." (PMID 34950770, 2022).
tumor (4 papers, 2019 to 2025). "Studies have found that ZCCHC12 is associated with the epithelial-mesenchymal transition (EMT) of tumor cells." (PMID 36126191, 2022). "A pattern plot of tumor stemness with ZCCHC12 expression, age, gender, and the stage was constructed by collating THCA clinical data and tumor stemness scores in TCGA." (PMID 37848968, 2023). "ZCCHC12 was negatively correlated with THCA tumor stemness (P = 3.82e-15; correlation coefficient = − 0.34)." (PMID 37848968, 2023). "In the present study, by analyzing a publicly available RNA-sequencing datasets from the GEO database, ZCCHC12 was found overexpressed in OS tissues than adjacent non-tumor samples." (PMID 36126191, 2022). "Also, our subsequent assays demonstrated that ZCCHC12 enhanced the proliferation, tumor growth and migration of OS cells." (PMID 36126191, 2022). "Moreover, our in vitro research showed that ZCCHC12 to promote tumor growth." (PMID 36126191, 2022). "Also, overexpression of ZCCHC12 promotes tumor growth in vivo." (PMID 36126191, 2022). "ZCCHC12 was identified by analyzing a previously performed RNA-Sequencing analysis (GEO, ID: GSE99671) in 18 OS tissues and matched adjacent non-tumor tissues." (PMID 36126191, 2022).
cancer (2 papers, 2021 to 2022). A tumor composed of atypical neoplastic, often pleomorphic cells that invade other tissues. "Given that EMT is closely associated with the motility of cancer cells, we examined ZCCHC12’s effect on EMT-related markers by qRT-PCR and western blot." (PMID 36126191, 2022). "The expression of ZCCHC12 was significantly increased in OS cells and tissues compared with non-cancer cells and tissues." (PMID 36126191, 2022).
ZCCHC12 also shares sentences with these, for which no sentence is quoted: developmental delay (1 paper); Intellectual disability (1).